IKZF1 (IKAROS family zinc finger 1)
Diseases named in the same sentence as IKZF1 in open-access papers (continued):
Sharing a sentence is not in itself a finding about the gene and the disease.
leukemia (continued). "These initial findings were confirmed by a contemporary study that investigated 40 leukemia patients, which identified again recurrent submicroscopic deletions in several genes linked to B-lineage development (PAX5, EBF1, TCF3, IKZF1 and others)." (PMID 27419633, 2016). "We found that the IKZF1-encoded protein, Ikaros, directly binds to the CRLF2 promoter and regulates CRLF2 expression in leukemia cells." (PMID 27391346, 2016). "In 2007, the first study demonstrating the importance of IKZF1 deletions (ΔIKZF1) in leukemia was published." (PMID 27419633, 2016). "Evidence shows that there are characteristics exclusive to specific leukemias, including deletion of BTG1 in B-cell leukemia, loss of IKZF1 with monosomy 7 in AML, and deletions involving IGH, TCR, IKZF1, and CDKN2A/B in CML-AP/CP." (PMID 27233483, 2016). "Although long-term follow-up information is not available for this case, we anticipate that the simultaneous presence of two high-risk genetic abnormalities in leukemia cells (RCSD1-ABL1 fusion and IKZF1 deletion) would predict a very high risk of relapse." (PMID 26600955, 2015). "These “Ph-like” leukemias share with Ph+ ALL a transcriptional signature indicative of kinase activation, co-occurring mutations in the B-cell transcription factor IKZF1, and a poor outcome." (PMID 24724051, 2014). "Many deletions (i.e., Cdkn2a, Ebf1, Pax5, Ikzf1) involved B-cell development genes and tumor suppressor genes, recapitulating deletions occurring in human leukemia." (PMID 23487523, 2012). "Recent evidence suggests that translocations act in concert with other genetic lesions to induce overt leukemia including deletion of genes such as cyclin-dependent kinase inhibitor 2A gene (CDKN2A) or the more recently described deletion of IKZF1 (Ikaros)." (PMID 21386967, 2011). "CK2 phosphorylates IKZF1 and impairs its function as a tumor suppressor in leukemia models." (PMID 39940843, 2025). "Early identification of IKZF1 deletions in B-ALL may inform the intensification of therapy and other potential treatment strategies to improve outcomes in this high-risk leukemia." (PMID 38255194, 2024). "None of the patients with identified FLT3 mutations presented recurrent rearrangements in B-ALL or alterations in the IKZF1, PAX5, or ERG genes, suggesting that FLT3 mutation may serve as the driving mechanism for leukemia in these cases." (PMID 39711880, 2024). "In summary, our study underscores the importance of leukemia subtype classification, characterization of IKZF1 alterations, and genomics-based analysis of cooperating lesions, in predicting the prognosis of pediatric patients with B-ALL undergoing MRD-directed therapy." (PMID 39606455, 2024). "IKZF1 deletions are more frequent in leukemia occurring in people of Hispanic origin." (PMID 38255194, 2024). "Flow cytometry of annexin V/PI staining was performed to evaluate the effects of various IKZF1 mutants on apoptosis of K562 and U937 leukaemia cells, which suggested that WT IKAROS and G158S could induce more apoptosis as compared with N159S and N159Y." (PMID 37345307, 2023). "IKZF1 deletion is a critical poor prognostic biomarker in ALL, the mutation of which drives normal lymphocytes to develop into leukemia.It was reported that HSCT could improve clinical outcomes of patients with IKZF1 mutation." (PMID 36226057, 2022). "The experimental leukemia presented with all the hallmarks of Ph-like “IKZF1 plus” human BCP-ALL in patients including a Ph-like expression signature, the spontaneous acquisition of the genomic loss of IKZF1, and the loss of the cell cycle regulator CDKN2A30." (PMID 35115489, 2022).
leukemia (continued). "In addition, Slinker was shown to be effective in visualising deletion events within transcriptomes of tumour samples in the important leukemia gene, IKZF1." (PMID 35035899, 2021). "In addition to Myc and Bcl2, other tumor-promoting genes such as Eef2 and Myh10 were upregulated in leukemia cells, whereas tumor suppressors such as Ikzf1, Ikzf2, Arid1b, Arid2, Samhd1, Bach2, and Myo18b were downregulated." (PMID 34907175, 2021). "Indeed, incubation of leukemia cells with the test dicarboximides resulted in downregulation of transcription factors IKZF1 and IKZF3, which are particularly important for development of T- and B-lymphocytes." (PMID 31487824, 2019). "Hence, while ETV6-RUNX1 expression in primary human leukemia cells associates with altered expression of a substantial fraction of the RUNX1 target genes, reduced function of IKZF1 or PAX5 had limited impact on the expression of their target genes." (PMID 31381561, 2019). "However, interestingly, in an in vitro model, loss of IKAROS (IKZF1), that is one of the main drivers of high-risk leukemia and whose activity restoration is attempted in preclinical models, was associated with decreased level of global H3K4 methylation." (PMID 28054944, 2017). "Mutations that lead to reduced IKZF1 function or expression have also been found to be a major genetic feature in human B-ALL and loss of IKZF1 also promotes the development of T-cell lymphoma/leukemia in mice, which suggests that IKZF1 acts as a tumor suppressor in T- and B-ALL." (PMID 39940843, 2025). "Additionally, IKZF1 deletion in B‐ALL shows a more stem cell‐like signature in gene expression profiling than the wild‐type IKZF1, and the expression of a stem cell program has been associated with drug resistance and poor outcomes in other types of leukemia." (PMID 36467841, 2022). "For instance, deletion of the IKZF1 gene in BCR-ABL1-positive BCP-ALL patients has been shown to not confer in vitro resistance to chemotherapy on its own, although resistance might occur due to new interactions between the leukemia cells presenting IKZF1 deletion and their BM microenvironment." (PMID 35804860, 2022). "There were 15 deaths in the no IKZF1 deletion cohort, 5 from leukemia and 10 from other causes." (PMID 27067989, 2016). "The results corroborate with those obtained after stratification, showing that IKZF1 and ARID5B rs10994982 variant alleles play a role in the susceptibility to MLL-germline leukemia while ARID5B rs10821936 confers increased risk to both MLL-germline and MLL-r leukemia." (PMID 24564228, 2014). "As expected, several previously reported genes with abnormal methylation in leukemias such as CPEB1, BLK, FLT3, ZCCHC7, EBF1, HDACs, IKZF1, RB1, CDK6, DOCK5, DPP10, MUC4, JAKs, KIT, KRAS, LINC01013, MAD1L1, NOTCH1, and STATs, among others, were also detected." (PMID 41226303, 2025). "Genes that have been reported as abnormally methylated in leukemia, including CPEB1, BLK, FLT3, PAX5, EBF1, HDACs, IKZF1, RB, etc., were also detected in this study." (PMID 41226303, 2025). "Ectopic expression of WT IKZF1 resulted in significant inhibition of cell growth and proliferation coinciding with its tumour‐suppression function, as measured by CCK‐8 assays in leukaemia cells K562 and U937." (PMID 37345307, 2023). "Amongst pluripotency genes, we have identified cancer genes (IDH2, NCOA2, IKZF1, BLM) which are already described as being involved in leukemia." (PMID 37174060, 2023). "Several genes that we identified included IDH2, NCOA2, IKZF1 and BLM described as being involved in leukemia." (PMID 37174060, 2023). "IKZF1 and IL7R synergistically activated downstream JAK/STAT5 and PI3K/Akt/mTOR signaling pathways to promote leukemia." (PMID 35419036, 2022). "As another interesting example, the module-level PPI feature module(IKZF1)–module(RB1) is one of the top-ranking features in K562, consistent with their critical functions in leukemia cells and their impacts on chromatin structure." (PMID 34570239, 2021).
leukemia (continued). "In leukemia, well-known oncogenes (such as MYC and NRF1) were among the top edge gainers, while the well-known tumor suppressor IKZF1 is the most significant edge loser." (PMID 32728046, 2020). "Selected dicarboximides displayed immunomodulatory activity and downregulated IKZF1 and IKZF3 transcription factors in K562 and MOLT-4 leukemia cells." (PMID 31487824, 2019). "In the case of Ikzf1, reduced expression was detected in all three leukemia samples, compared to BCP cells from transgene-negative BALB/c mice." (PMID 38519798, 2024). "Based on the negative prognostic significance of IKZF1-deleted B-ALL, several trials have utilized this approach for patients with IKZF1 deletions, including the DFCI ALL Consortium (NCT03020030), AIEOP-BFM (NCT03643276), DCOG, and the Malaysia-Singapore (MASPORE) leukemia study group." (PMID 38255194, 2024). "It should be noted that neither constitutional nor acquired deletions of IKZF1 seem to be sufficient to trigger the onset of leukemia." (PMID 36834692, 2023). "Full transformation associates with transcriptional upregulation of oncogenes such as Myc or Bcl2, downregulation of tumor suppressors such as Ikzf1 or Arid2, and major IL-7R signaling upregulation (involving JAK/STAT5 and PI3K/mTOR), required for leukemia cell viability." (PMID 34907175, 2021). "We determined MRD15 and MRD33 levels to investigate if initial response to treatment contributed to leukemia recurrence in CRLF2pos/IKZF1Δ patients by analyzing blast clearance in the bone marrow of CRFL2pos patients with or without IKZF1 deletions." (PMID 29899835, 2018). "Multivariate analyses were done to identify associations between IKZF1 deletion and other variables on non-relapse mortality (NRM), cumulative incidence of relapse (CIR), leukemia-free survival (LFS) and survival." (PMID 27067989, 2016). "Strikingly, this IGH germline ALL group exhibited a high frequency of IKZF1 deletions and non-V(D)J rearrangements including CRLF2-IGH, EPOR-IGH, and EBF1-PDGFRß that can be exploited as leukemia-specific targets in clinical diagnostics of MRD." (PMID 31784504, 2019).
acute lymphoblastic leukemia (97 papers, 2012 to 2026). Leukemia with an acute onset, characterized by the presence of lymphoblasts in the bone marrow and the peripheral blood. "IKZF1 deletions were known to be associated with poor survival in acute lymphoblastic leukemia (ALL); but it has also been identified in both MBC and LBC." (PMID 39518058, 2024). "The GWAS catalog results are generally consistent, with only one variation (IKZF1:c.*1656T>C) associated with Acute Lymphoblastic Leukemia providing contradictory information." (PMID 37946154, 2023). "More than 70% of Ph+ and Ph-like cases of acute lymphoblastic leukemia exhibit IKZF1 gene variants, which are linked to worse treatment outcomes in both childhood and adult B-cell precursor acute lymphoblastic leukemia." (PMID 36834692, 2023). "Genetic lesions of IKZF1 are frequent events and well-established markers of adverse risk in acute lymphoblastic leukemia." (PMID 37833543, 2023). "An association of deletions in the IKZF1 gene (IKZF1del) with poor prognosis in acute lymphoblastic leukemia (ALL) has been demonstrated." (PMID 35805054, 2022). "IKZF1 is a relevant gene associated with the pathogenesis of acute lymphoblastic leukemia, and the rs4132601 (T>G) and rs11978267 (A>G) polymorphisms have been associated with the development of this disease in several populations." (PMID 33452870, 2021). "Associations between IKZF1 gene variants and Acute Lymphoblastic Leukemia (ALL) was recently reported." (PMID 31604453, 2019). "Somatic defects in IKZF1, a hematopoietic zinc finger transcription factor, have been linked to acute lymphoblastic leukemia (ALL) for several years and have been proven to harbor negative prognostic effects." (PMID 30443258, 2018). "More recently, genome wide association studies identified significant associations between genetic polymorphisms in ARID5B e IKZF1 and acute lymphoblastic leukaemia, but only a few studies have replicated these results until now." (PMID 26045716, 2015). "Genome wide association studies (GWAS) have established association of ARID5B and IKZF1 variants with childhood acute lymphoblastic leukemia (ALL)." (PMID 25310577, 2014). "Acute Lymphoblastic Leukemia (ALL) is associated with mutations like IKZF1 and PAX5, along with radiation and pesticides, but its exact causes remain unclear in many cases." (PMID 41362667, 2025). "Notably, studies affirm that the loss or malfunction of IKZF1 is closely linked to drug resistance, heightened relapse rates, and unfavorable prognosis in acute lymphocytic leukemia (ALL) and acute myeloid leukemia (AML)." (PMID 39759140, 2024). "In BCR-ABL-positive acute lymphoblast leukemia cells, the association of deletion of IKZF1 with adverse outcome may be due to the impairment of HR." (PMID 35414773, 2022). "However, these variant types can be clinically important, for example, IKZF1 deletions in acute lymphoblastic leukaemia, FLT3 internal tandem duplications (ITDs) and MLL partial tandem duplications (PTDs) in acute myeloid leukaemia." (PMID 34686194, 2021). "Mutations in the transcription factors PAX5 and IKZF1 are commonly seen in acute lymphoblastic leukaemia, suggesting that their expression may confer a selective disadvantage." (PMID 34163480, 2021). "Notably, deletions and mutations in the IKZF1 locus that cause reduction of IKAROS activity are highly associated with development of acute lymphoblastic leukemias in humans." (PMID 26135129, 2015). "There is overwhelming evidence that IKZF1 variants are associated with childhood acute lymphoblastic leukaemia and several diseases with an autoimmune component: systemic lupus erythematosus (SLE), type 1 diabetes, Crohn's disease, systemic sclerosis, malaria and erythrocyte mean corpuscular volume." (PMID 23382691, 2013).
acute lymphoblastic leukemia (continued). "The IKZF1 gene encodes IKAROS – a DNA binding protein that acts as a tumor suppressor in T-cell acute lymphoblastic leukemia (T-ALL)." (PMID 40555735, 2025). "IKZF1 haploinsufficiency and dominant negative mutations are frequent in pre-B cell acute lymphoblastic leukemia (B-ALL), where they predict poor patient outcomes." (PMID 39437550, 2025). "Alterations in IKZF1, such as deletions, is implicated in the pathogenesis of B-progenitor acute lymphoblastic leukemia (B-ALL)." (PMID 38791993, 2024). "In acute lymphoblastic leukemia (ALL) focal deletions in IKAROS family zinc finger 1 (IKZF1) result in the loss of zinc-finger DNA-binding domains and a dominant negative isoform that is associated with higher rates of relapse and poorer patient outcomes." (PMID 37767021, 2023). "Inactivation of IKAROS by a recurrent genetic alteration in the IKZF1 gene is seen in nearly 4–5% of adult and pediatric T- cell Acute Lymphoblastic Leukemia (T-ALL) and is associated with poor outcome." (PMID 33467550, 2021). "IKZF1 (IKAROS Family Zinc Finger 1) (OMIM 603023) is considered a relevant gene associated with acute lymphoblastic leukemia (ALL), which is located on 7p12.2 and contains eight exons." (PMID 33452870, 2021). "Pediatric B-cell precursor acute lymphoblastic leukemia (BCP-ALL) is associated with a high frequency of copy number alterations (CNAs) in IKZF1, EBF1, PAX5, CDKN2A/B, RB1, BTG1, ETV6, and/or the PAR1 region (henceforth: B-cell development genes)." (PMID 30874617, 2019). "Genome-wide association studies (GWAS) have identified that frequent polymorphisms in ARID5B and IKZF1, two genes involved in lymphoid differentiation, increase the risk of childhood acute lymphoblastic leukemia (ALL)." (PMID 25806972, 2015). "New genetic markers for adult acute lymphoblastic leukemia (ALL) have been found to have prognostic impact, such as the lymphoid transcription factor gene IKZF1 alterations, which are associated with a high rate of leukemic relapse in B-ALL." (PMID 23773228, 2013). "This study aimed to evaluate the association of single nucleotide polymorphisms (SNPs) in IKZF1, ARID5B, and CEBPE with acute lymphoblastic leukemia (ALL) susceptibility in Chinese children." (PMID 41488748, 2025). "The deletions of IKZF1 have an established significance in acute lymphoblastic leukemia, while reports on its prevalence and prognostic significance among ALL subtypes and regions vary." (PMID 39272737, 2024). "IKZF1, a zinc finger DNA-binding transcription factor, is responsible for normal lymphopoiesis and functions as a tumor suppressor protein in acute lymphoblastic leukemia." (PMID 38530845, 2024). "There have been conflicting reports regarding the incidence and, particularly, the significance of IKZF1 deletions in acute lymphoblastic leukemia." (PMID 39272737, 2024). "Philadelphia-like acute lymphoblastic leukemia (Ph-like ALL) is a high-risk subtype, with approximately half of cases characterized by CRLF2 overexpression and frequent concomitant IKZF1 deletions." (PMID 38370004, 2024). "IKZF1 is known to be an important factor in acute lymphoblastic leukemia, IRF4 drives tumor growth in several lymphoid malignancies, and PIK3CG is closely associated with claudin‐low breast cancer migration." (PMID 38506253, 2024). "Deletion of IKZF1, most frequently whole gene deletion, is found in 25–35% of adults and 12–17% of children with acute lymphoid leukemia and confers a poorer prognosis." (PMID 37686670, 2023). "As many patients with BCR-ABL1 lymphoblastic leukemia demonstrate durable responses to treatment, some of them must harbor IKZF1 losses given the high frequency of this alteration." (PMID 37337105, 2023). "A classic example in pediatric acute lymphoblastic leukemia involves the IKZF1 gene, whereby variably deleted exons generate multiple alternatively spliced transcript isoforms." (PMID 37686670, 2023).